CYLD (CYLD lysine 63 deubiquitinase)
Description:
Deubiquitinase that specifically cleaves 'Lys-63'- and linear 'Met-1'-linked polyubiquitin chains and is involved in NF-kappa-B activation and TNF-induced necroptosis. Negatively regulates NF-kappa-B activation by deubiquitinating upstream signaling factors. Contributes to the regulation of cell survival, proliferation and differentiation via its effects on NF-kappa-B activation. Negative regulator of Wnt signaling. Inhibits HDAC6 and thereby promotes acetylation of alpha-tubulin and stabilization of microtubules. Plays a role in the regulation of microtubule dynamics, and thereby contributes to the regulation of cell proliferation, cell polarization, cell migration, and angiogenesis. Required for normal cell cycle progress and normal cytokinesis. Inhibits nuclear translocation of NF-kappa-B. Plays a role in the regulation of inflammation and the innate immune response, via its effects on NF-kappa-B activation. Dispensable for the maturation of intrathymic natural killer cells, but required for the continued survival of immature natural killer cells (By similarity). Negatively regulates TNFRSF11A signaling and osteoclastogenesis (By similarity). Involved in the regulation of ciliogenesis, allowing ciliary basal bodies to migrate and dock to the plasma membrane; this process does not depend on NF-kappa-B activation (By similarity). Ability to remove linear ('Met-1'-linked) polyubiquitin chains regulates innate immunity and TNF-induced necroptosis: recruited to the LUBAC complex via interaction with SPATA2 and restricts linear polyubiquitin formation on target proteins. Regulates innate immunity by restricting linear polyubiquitin formation on RIPK2 in response to NOD2 stimulation. Involved in TNF-induced necroptosis by removing linear ('Met-1'-linked) polyubiquitin chains from RIPK1, thereby regulating the kinase activity of RIPK1 (By similarity). Negatively regulates intestinal inflammation by removing 'Lys-63' linked polyubiquitin chain of NLRP6, thereby reducing the interaction between NLRP6 and PYCARD/ASC and formation of the NLRP6 inflammasome (By similarity). Does not catalyze deubiquitination of heterotypic 'Lys-63'-/'Lys-48'-linked branched ubiquitin chains. Removes 'Lys-63' linked polyubiquitin chain of MAP3K7, which inhibits phosphorylation and blocks downstream activation of the JNK-p38 kinase cascades. Also removes 'Lys-63'-linked polyubiquitin chains of MAP3K1 and MA3P3K3, which inhibit their interaction with MAP2K1 and MAP2K2.
Synonyms: CYLD1; KIAA0849; USPL2; BRSS; CDMT; CYLDI; EAC; FTDALS8; MFT; MFT1; SBS; TEM
Tractability: Small molecule: it has a high-quality binding pocket. Antibody: UniProt places it where antibodies can reach, with medium confidence; its Gene Ontology location is reachable by antibodies, with medium confidence. PROTAC: UniProt records ubiquitination sites on it; ubiquitination databases record sites on it.
Target class: Enzyme; Hydrolase
Gene: Protein-coding gene on chromosome 16 (50,742,032 to 50,801,935, forward strand). Ensembl gene ENSG00000083799.
Subcellular location: Cytoplasm; Cytoplasm, perinuclear region; Cytoplasm, cytoskeleton; Cell membrane; Cytoplasm, cytoskeleton, microtubule organizing center, centrosome; Cytoplasm, cytoskeleton, spindle; Cytoplasm, cytoskeleton, cilium basal body
Subcellular location (Human Protein Atlas): Centriolar satellite; Basal body; Nucleoplasm; Primary cilium transition zone; Principal piece
Pathways (Reactome):
Signal Transduction: Regulation of TNFR1 signaling; TNFR1-induced NF-kappa-B signaling pathway; TNFR1-induced proapoptotic signaling
Immune System: NOD1/2 Signaling Pathway; Negative regulators of DDX58/IFIH1 signaling
Metabolism of proteins: Ub-specific processing proteases
Gene Ontology:
Molecular function: cysteine-type deubiquitinase activity; K63-linked deubiquitinase activity; Met1-linked polyubiquitin deubiquitinase activity; proline-rich region binding; protein binding; protein kinase binding; zinc ion binding
Biological process: innate immune response; negative regulation of canonical NF-kappaB signal transduction; negative regulation of canonical Wnt signaling pathway; negative regulation of JNK cascade; negative regulation of non-canonical NF-kappaB signal transduction; negative regulation of p38MAPK cascade; positive regulation of extrinsic apoptotic signaling pathway; protein deubiquitination; protein linear deubiquitination; regulation of inflammatory response; regulation of intrinsic apoptotic signaling pathway; regulation of microtubule cytoskeleton organization; regulation of mitotic cell cycle; regulation of necroptotic process; regulation of tumor necrosis factor-mediated signaling pathway; necroptotic process; negative regulation of inflammatory response; negative regulation of interleukin-18-mediated signaling pathway; negative regulation of type I interferon production; nucleotide-binding domain, leucine rich repeat containing receptor signaling pathway; protein K63-linked deubiquitination; regulation of cilium assembly
Cellular component: centriolar satellite; centrosome; cytoplasm; cytoplasmic microtubule; cytoplasmic side of plasma membrane; cytosol; midbody; spindle; ciliary basal body; ciliary tip; cytoskeleton; organelle; perinuclear region of cytoplasm; plasma membrane
Genetic constraint (gnomAD): Loss-of-function variants: 16 observed, 74.74 expected, observed/expected ratio (o/e) 0.21, 90% interval 0.14 to 0.32. The upper end of that interval is the gene's LOEUF score, 0.32, which puts it in group 1 of 6, group 1 being the genes least tolerant of losing a copy. Missense variants: 601 observed, 1,011.4 expected, observed/expected ratio (o/e) 0.59, 90% interval 0.56 to 0.64. Synonymous variants: 321 observed, 360.16 expected, observed/expected ratio (o/e) 0.89, 90% interval 0.81 to 0.98.
Gene-disease validity (ClinGen):
ClinGen rates the evidence that CYLD causes each of these diseases.
Brooke-Spiegler syndrome (autosomal dominant): Definitive. Brooke-Spiegler syndrome (BSS) is an inherited predisposition syndrome presenting with skin appendage tumors, namely cylindromas, spiradenomas and trichoepitheliomas.
frontotemporal dementia and/or amyotrophic lateral sclerosis 8 (autosomal dominant): Limited.
Cancer hallmarks: escaping programmed cell death (suppresses); suppression of growth (promotes); invasion and metastasis (suppresses); angiogenesis (suppresses); tumour promoting inflammation (suppresses); angiogenesis (promotes); tumour promoting inflammation
Homologues: Orthologues: chimpanzee CYLD (100% identical), macaque CYLD (99% identical), dog CYLD (97% identical), rabbit CYLD (97% identical), guinea pig CYLD (96% identical), pig CYLD (96% identical), mouse Cyld (95% identical), rat Cyld (94% identical), tropical clawed frog cyld (81% identical), zebrafish cyld (69% identical), Drosophila melanogaster CYLD (27% identical), Caenorhabditis elegans cyld-1 (23% identical).
Diseases named in the same sentence as CYLD in open-access papers:
CYLD is named in the same sentence as 201 diseases in open-access papers, as found by Europe PMC text mining. Sharing a sentence is not in itself a finding about the gene and the disease. The quoted sentences say what the papers report.
familial cylindromatosis (44 papers, 2009 to 2026). "CYLD is a tumor suppressor mutated in familial cylindromatosis, a genetic condition that predisposes patients to neoplasms of the skin, and more recently, mutations in CYLD have been described in other cancers." (PMID 40799389, 2025). "CYLD was originally identified as a tumor suppressor gene mutated in familial cylindromatosis, a genetic condition characterized by the presence of multiple benign skin tumors that typically occur on the scalp and neck, termed cylindromas." (PMID 39945824, 2025). "Trichoblastoma (TB) is a benign primitive follicular neoplasm that can occur in the setting of Brooke-Spiegler syndrome (CYLD mutations), in association with nevus sebaceous (mosaic HRAS mutations), or sporadically." (PMID 41203975, 2025). "Our patient was diagnosed with CYLD cutaneous syndrome, with a molecular finding of a variant in the CYLD gene." (PMID 39430072, 2024). "These tumours can present as single or multiple nodules, with the latter form often linked to CYLD gene mutations, particularly in the context of CYLD cutaneous syndrome." (PMID 39355720, 2024). "CYLD cutaneous syndrome is caused by pathogenic variants in the CYLD gene, following an autosomal dominant inheritance pattern." (PMID 39430072, 2024). "CYLD is also known a tumor suppressor that is identified in familial cylindromatosis and Brooke-Spiegler syndrome, due to inherited CYLD gene mutation." (PMID 37549179, 2023). "Compared to other genes, CYLD variants have thus far only been linked to Brooke-Spiegler syndrome, familial cylindromatosis, and multiple familial piloepitheliomas." (PMID 37090690, 2023). "Initially identified in familial cylindromatosis (FC), a skin appendage tumor typically manifesting on the scalp, CYLD is implicated in a genetic syndrome thought to originate from hair follicle stem cells." (PMID 37176077, 2023). "Mutations in CYLD account for what had previously been three skin appendage tumour syndromes, familial cylindromatosis, Spiegler-Brooke syndrome (BSS), and multiple familial trichoepithelioma." (PMID 36733767, 2022). "As a tumor suppressor, CYLD was identified as mutated in familial cylindromatosis and loss of CYLD has also been implicated in several other malignancies, such as colon and hepatocellular carcinomas, multiple myeloma, melanoma, and breast cancer." (PMID 33654169, 2021). "If the lesion is a part of Brooke-Spiegler syndrome, which manifests as numerous adnexal lesions (mostly benign) as spiradenoma, cylindroma, spiradenocylindroma, and trichoepithelioma, the CYLD mutation is present." (PMID 34064849, 2021). "CYLD mutations have been described in familial cylindromatosis, familial trichoepithelioma, and Brooke–Spiegler syndrome, in which patients have a predisposition to develop multiple skin tumors of the neck and head." (PMID 32549302, 2020). "The preponderance of clinical studies of CYLD mutation have concerned syndromic manifestations of familial cylindromatosis, Brooke-Spiegler syndrome, and multiple familial trichoepitheliomas." (PMID 32461623, 2020). "Brooke-Spiegler syndrome) carry germline mutations in the tumor suppressor CYLD and develop multiple skin tumors with diverse histophenotypes." (PMID 31624251, 2019). "Almost all CYLD cutaneous syndrome patients do carry a germline mutation of CYLD which is inheritable." (PMID 31093340, 2016). "In contrast CYLD is a tumour suppressor, whose loss leads to familial cylindromatosis, a skin tumour hereditary disorder, but that also controls NF-κB activation." (PMID 27597804, 2016). "Mutations and deletions in CYLD have been reported in Brooke-Spiegler syndrome (BSS), familial trichoepithelioma and malignant transformation." (PMID 28031783, 2016). "Germline CYLD mutation is associated with the development of a rare inheritable syndrome, called the CYLD cutaneous syndrome." (PMID 31093340, 2016).
familial cylindromatosis (continued). "CYLD has initially been identified as a tumor suppressor gene mutated in familial cylindromatosis, an autosomal-dominant predisposition to multiple tumors of skin appendages." (PMID 25329885, 2014). "CYLD is a familial cylindromatosis tumor suppressor gene, mutations in the CYLD gene cause human familial cylindromatosis." (PMID 24594309, 2014). "CYLD is a tumor suppressor gene mutated in familial cylindromatosis, also called “turban tumor syndrome,” an autosomal-dominant condition that confers a predisposition to multiple skin tumors." (PMID 20414373, 2010). "The deletion region also includes the genes NOD2 associated with Blau syndrome (OMIM 266600) and CYLD associated with Brooke-Spiegler syndrome (MIM 605041)." (PMID 20003547, 2009). "Heterozygous loss of function mutations in CYLD cause Brooke-Spiegler syndrome, which is characterized by a number of rare skin appendage tumors such as cylindroma, trichoepithelioma, and spiradenoma." (PMID 20003547, 2009). "Patients with Brooke-Spiegler syndrome, a rare, inherited condition attributed to germline disruptive variants in the CYLD gene, develop tumours primarily on the face, scalp and neck, with cylindromas, spiradenomas and trichoepithelioma as the most common presentation, and rarely, SGTs52,53." (PMID 40389436, 2025). "It has also been reported that mutations in CYLD are implicated in multiple skin appendage tumors, including familial trichoepitheliomas and spiradenomas, collectively unified under the umbrella term CYLD cutaneous syndrome." (PMID 39945824, 2025). "Inactivating mutations of CYLD underlie the CYLD cutaneous syndrome, a disease characterized by the development of benign skin tumors of the hair follicles including multiple familial trichoepithelioma, the Brooke–Spiegler syndrome, and familial cylindromatosis." (PMID 39958342, 2025). "CYLD on chromosome 16q has been implicated in Brooke-Spiegler syndrome." (PMID 39735034, 2024). "CYLD gene is more commonly discussed in association with Brooke-Spiegler syndrome (BSS)." (PMID 39376856, 2024). "Lesions such as spiradenoma or cylindroma may develop as a part of Brooke-Spiegler syndrome, a genetic disorder with germline mutations in the CYLD (CYLD Lysine 63 Deubiquitinase) gene." (PMID 34064849, 2021). "Loss of functional CYLD causes a disease known as Brooke-Spiegler syndrome (BSS)." (PMID 25565632, 2014). "Multiple cylindromas may arise in patients with CYLD cutaneous syndrome, including familial cylindromatosis, multiple familial trichoepithelioma and Brooke-Spiegler syndrome, which is characterized by a germline mutation within the tumor suppressor gene CYLD." (PMID 37389703, 2023). "In addition, recent discoveries of gain-of-function germline pathogenic CYLD variants in patients with a neurodegenerative phenotype contrast with the more widely known loss-of-function mutations seen in patients with CYLD cutaneous syndrome and with sporadic cancers." (PMID 37387450, 2023). "Loss of CYLD function is associated with tumor growth and dysregulated tropomyosin kinase (TRK) signaling in CYLD cutaneous syndrome." (PMID 41168867, 2025). "In contrast, certain authors tend to label this condition as CYLD cutaneous syndrome (CSS) based on the key role of the CYLD gene on chromosome 16q12-q13 in disease development." (PMID 38673513, 2024). "The pathogenesis is not entirely understood, but a defect in the tumor suppressor gene, CYLD, is thought to contribute to their development in Brooke-Spiegler syndrome, which also features multiple spiradenomas." (PMID 34064849, 2021). "A mutant tumor suppressor gene CYLD has been identified in familial cylindromatosis and CYLD is downregulated in multiple cancer types." (PMID 31396277, 2019). "Cylindromatosis (turban tumor syndrome), also called CYLD, was originally identified as tumor suppressor gene, a mutation of which causes tumors of the hair follicles (cylindromas)." (PMID 28203236, 2017).
familial cylindromatosis (continued). "Although the genetic link between CYLD defects and the CYLD cutaneous syndrome has been identified, there remain many interesting questions to be answered regarding this peculiar syndrome." (PMID 31093340, 2016). "Originally, CYLD has been described as a tumor suppressor gene in a rare tumor disease, called familial cylindromatosis (Brooke-Spiegler Syndrome)." (PMID 25329885, 2014). "TBC has been linked to mutations in the CYLD gene and is observed in patients with multiple familial trichoepithelioma (MFT) and Brooke-Spiegler syndrome, which is an autosomal dominant disease characterized by the growth of trichoepitheliomas, spiradenomas, cylindromas, or their combination." (PMID 39050309, 2024). "CYLD was originally identified as a tumor suppressor in familial cylindromatosis, a skin tumor disorder, caused by CYLD mutations that lead to lack of DUB activity." (PMID 36846565, 2023). "Thus, germline defects of CYLD in patients with the CYLD cutaneous syndrome are mainly presented with head and neck tumors or tumors in regions with lots of hair follicles." (PMID 31093340, 2016). "Therefore, it is believed that genomic aberrations of CYLD may alter NF-kB signaling activity, which may also contribute to the pathophysiology of the CYLD cutaneous syndrome and tumor formation." (PMID 31093340, 2016). "The disease is associated with various mutations in the cylindromatosis (CYLD; MIM 605018) gene that are also responsible for familial cylindromatosis (FC) and Brooke-Spiegler syndrome (BSS)." (PMID 26861065, 2016).